CRP (C-reactive protein)
Diseases named in the same sentence as CRP in open-access papers (continued):
Sharing a sentence is not in itself a finding about the gene and the disease.
diabetes (continued). "Our study design also included controlling for factors that could modify CRP expression as well as risk of AMD, including CFH genotype, smoking, body mass index (BMI), and diabetes, reducing the likelihood of observing false positive correlations." (PMID 18704199, 2008). "These include age, body mass index (BMI), smoking, SBP and diastolic blood pressure (DBP), fasting plasma cholesterol, high-density lipoprotein (HDL) cholesterol, triglycerides, C-reactive protein (CRP), homocysteine, lipoprotein (a) (Lp(a)), fibrinogen, hypertension, and diabetes." (PMID 18482449, 2008). "Compared with those who did not agree to storage, adjusted mean values for those who agreed to storage ranged from 9.7 percent lower for C-reactive protein to 8.7 percent higher for fasting insulin (among participants with diabetes), with most differences within ± 5 percent." (PMID 17822566, 2007). "Although inflammation represents an important feature in all stages of atherogenesis and its complications, we could not demonstrate an association between infection markers, sero-status and levels of CRP, even after consideration of history of diabetes." (PMID 16608530, 2006). "ROC curves were generated to evaluate the baseline risk model consisting of age,sex, smoking status, BMI, diabetes duration, hypertension, coronary heartdisease, cerebrovascular disease, MAP, fasting glucose level, HbA1c, and thefitting model of the baseline risk model and CRP/albumin ratio." (PMID 40622101, 2025). "Second-generation antipsychotics may exacerbate metabolic and inflammatory complications, with clozapine and olanzapine particularly implicated in insulin-resistance, poor glucose control, weight gain, type 2 diabetes mellitus, and increased C-reactive protein (CRP) and inflammatory cytokines." (PMID 41356674, 2025). "The associations of HS with lower hepatic insulin resistance, increased whole body sensitivity and metabolic health including lower prevalence of MetS and lower CRP were independent of classical diabetes risk factors including family history of diabetes, age, ethnicity, and pre-pregnancy BMI." (PMID 41276872, 2025). "Moreover, increased CRP levels may be a biomarker of insufficient control of various diseases, e.g., diabetes." (PMID 40137683, 2025). "C-reactive protein-triglyceride glucose index (CTI) represents an innovative composite marker that integrates key components - C-reactive protein (CRP), triglycerides, and glucose—each of which has been robustly associated with diabetes, non-alcoholic fatty liver disease, and cardiovascular events." (PMID 41229520, 2025). "Furthermore, intraoperative non-response to ibutilide, as well as older age, the presence of diabetes, larger left atrial diameter, higher serum sST2 and hs-CRP levels, and elevated CHA2DS2-VASc scores, each independently portended an increased risk of AF recurrence following catheter ablation." (PMID 40842477, 2025). "Finally, subgroup analyses involving patients with comorbidities, such as diabetes or chronic kidney disease, may help clarify the prognostic relevance of CRP across different clinical populations." (PMID 41200636, 2025). "However, the A+/N+ subgroup was less likely to have hypertension or diabetes or to use antihypertensive or lipid-lowering medication, had lower triglycerides, fasting glucose, hs-CRP, BMI, and waist-to-hip ratio, and had higher HDL-C than the A−/N+ and A−/N− subgroups." (PMID 39983616, 2025). "The hazard ratio associated with vitamin D deficiency for incident diabetes was similar between younger and older adults regardless of CRP z-scores, but was significantly higher at low z-scores of CRP comparing frail or pre-frail older adults to older adults who were non-frail." (PMID 39662157, 2025).
diabetes (continued). "While the underlying mechanisms remain unclear, daytime napping—often viewed as a compensatory response to sleep deprivation or poor sleep quality—has been associated with elevated levels of inflammatory markers, such as serum C-reactive protein, which may contribute to the development of diabetes." (PMID 41419872, 2025). "Earlier age at menarche was associated with higher CRP, fasting insulin, and fasting glucose among US women aged median 44 years (IQR, 33-62) after adjusting for age, race/ethnicity, education, parity, menopause status, family history of diabetes, smoking status, physical activity, alcohol, and BMI." (PMID 38912813, 2025). "Additionally, serum uric acid (UA), high-sensitivity C-reactive protein (hs-CRP), and self-reported chronic conditions, such as hyperlipidemia, diabetes, hypertension, cancer, chronic lung disease, liver disease, and chronic kidney disease, were also documented." (PMID 40727574, 2025). "Moreover, no mediating effects were observed for hs-CRP, obesity, central obesity, diabetes or hypertension in the association between DII and CVD." (PMID 40614606, 2025). "Since CRP is part of the initial innate immune system response to inflammatory triggers, reduction in CRP levels could suggest a lower incidence of acute and initial-phase diabetes onset and attenuation of the perpetual inflammatory cycle." (PMID 40943351, 2025). "Moreover, the anti-inflammatory properties of sweet cherries may help manage conditions like diabetes by reducing markers of inflammation such as C-reactive protein (CRP) and interleukin-6 (IL-6)." (PMID 39519493, 2024). "These include age, diabetes mellitus, renal disease, history of catheter-associated infection, hypertension, dialysis duration, catheter site, catheter duration, number of catheterizations, catheter type, CD4+ cell, ALB, CRP, Hb, PCT, inadequate hand hygiene, and APACHE II scores." (PMID 38536779, 2024). "Furthermore, diabetes is known to induce pro-inflammatory markers, such as cytokines, including several interleukins and tumor necrosis factor, by the activation of various biochemical parameters, such as C-reactive protein." (PMID 39257852, 2024). "C-reactive protein levels, indicative of inflammation, were significantly higher in the T1D (27.4 mg/L) and T2D (38.2 mg/L) groups compared to the no diabetes group (15.2 mg/L), suggesting more pronounced inflammatory responses in patients with diabetes (p < 0.001)." (PMID 38399498, 2024). "The multinomial univariable logistic regression and contingency table analysis detected the higher risk factor of spine infection, the absence of diabetes (p = 0.029), higher Day 1 CRP levels (p = 0.014), and the presence of DISH (p = 0.022) significantly differentiated the spinal infection group." (PMID 39619206, 2024). "Most of the measured parameters were not normally distributed (i.e., non-parametric), which may in part explain the lack of statistically significant differences between tertiles, for parameters such as duration of diabetes, and the levels of HbA1c, CRP and TG." (PMID 39796144, 2024). "The transition from prediabetes to diabetes has been linked to the presence of both pro- and anti-inflammatory indicators, including adiponectin, the recently discovered extracellular AGE-binding receptor (EN-RAGE), interleukin-6 (IL-6), IL-13, CRP, IL-18, IL-1 receptor antagonist, and neopterin." (PMID 39031306, 2024). "Interestingly, when we look at the disease association data, we can see that ENPP7 has the lowest text mining score for all metrics but the highest fraction of diabetes co-mentions to all-disease co-mentions except for CRP, which also has the highest total number of co-mentions." (PMID 37590326, 2023). "In addition, FIB-5 index combined with CRP could also be used for risk stratification when analyzing subgroups such as age, sex, BMI, LVEF, history of hypertension, and diabetes mellitus." (PMID 37794360, 2023).
diabetes (continued). "In this cross-sectional analysis of AI participants from the SHFS, rs3740393 modified the association of reported Mg intake with IL-6 (but not CRP), after adjustment for factors known to be associated with Mg intake and inflammation, including dietary factors, prevalent diabetes, and prevalent CVD." (PMID 38128021, 2023). "To date, no studies have investigated the association between other states of chronic hyperglycaemia, such as prediabetes and undiagnosed DM, and acute-on-chronic hyperglycaemia and CRP levels during admission in CAP." (PMID 38202252, 2023). "Given the important role of CRP regarding body fat, insulin resistance, diabetes and CVD, longitudinal studies could assist to better understand the underlying mechanisms and help to guide early risk stratification and intervention for this young but high-risk population." (PMID 37891561, 2023). "The following factors were applied in the cluster analysis: age, sex, diabetes mellitus, hypertension, atrial fibrillation, dementia, myocardial infarction, concurrent bacterial infection, stroke, dyslipidemia, NT-proBNP, creatinine, neutrophils, eGFR, CRP, and systolic BP." (PMID 37760914, 2023). "However, the median weight, waist circumference, BMI, serum albumin, C-reactive protein, HbA1c, fasting glucose, blood urea, eGFR, and serum lipids of the type 2 diabetes mellitus group were significantly different from those of the control subjects (p < 0.05 for all)." (PMID 37762893, 2023). "Moreover, this predictive value of serum miR-183-5p level was independent of age, sex, BMI, diabetes, and hs-CRP, which are well-established risk factors of CAD." (PMID 37396583, 2023). "However, the association was attenuated after adjustment for certain CV risk factors and biomarkers, including diabetes mellitus (DM), hypertension (HTN), dyslipidemia, estimated glomerular filtration rate, smoking, and serum high-sensitivity C-reactive protein (CRP) levels." (PMID 37240626, 2023). "Additionally, a model of C-reactive protein, lactate dehydrogenase, and the presence of diabetes may play a predictive role in determining the future need for intubation." (PMID 35274051, 2022). "However, the levels of hs-CRP were higher with prevalent diabetes and dyslipidemia." (PMID 35399841, 2022). "C-reactive protein (CRP) is independently associated with the occurrence of atrial fibrillation, and elevated tumor necrosis factor-α (TNF-α) and interleukin-6 (IL-6) also increase the risk of type 2 diabetes mellitus, coronary heart disease and atherosclerosis." (PMID 36361072, 2022). "Patients who also had diabetes, hypertension, proteinuric kidney disease, chronic kidney disease, diverticular disease and gastro-oesophageal reflex disorders had a higher risk of CVD, as do patients with low albumin, raised C-reactive protein and raised International Normalized Ratio levels." (PMID 34980174, 2022). "Besides, other factors, such as hydronephrosis, diabetes, C-reactive protein, and so on, which may influence the systematic condition and local urological condition, have been reported to result in infectious events after surgery." (PMID 35495750, 2022). "In a univariate survival analysis, it was found that male gender, age over 65 years old, complications such as hypertension or diabetes, elevation in WBC count or neutrophil count, decrease in lymphocyte count, thrombocytopenia and increase in CRP level may lead to increased risk of mortality." (PMID 35591765, 2022). "Hence, cytokine CRP and insulin expression in saliva at this age could potentially predict future progression to serious metabolic diseases, such as diabetes and cardiovascular diseases." (PMID 35757631, 2022). "Interestingly, both plasma concentrations and total taurine losses were associated with severe fatigue, independent of age, sex, body mass index, dialysis vintage, hemoglobin concentration, C-reactive protein concentration, presence of cardiovascular disease, and presence of diabetes." (PMID 35889768, 2022).
diabetes (continued). "In individuals suffering from type 2 diabetes mellitus, however, the balance is tilted towards the proinflammatory side, manifested by an upregulation of proinflammatory intracellular pathways and an elevation in circulating inflammatory markers, such as C-reactive protein, IL-6, and TNFα." (PMID 35163309, 2022). "28-day mortality subgroup analysis of those with a Stage 3a-5 kidney disease found that: first wave patients; aged 85–94, female sex; never and current smoker; CRP ≥ 40 mg/dL; no hypertension; no diabetes; coronary artery disease; and CFS 4 were associated with increased mortality." (PMID 35151257, 2022). "The high median levels of CRP observed in our cohort, given the young median age of the enrolled patients, are probably not due to aging-related diseases (i.e., cardiovascular disease, hypertension, diabetes mellitus, and kidney disease), but to inflammation related to the neoplasm." (PMID 35330364, 2022). "Rigorous scrutiny of clinicopathological features of COVID-19 infected cancer patients with diabetes especially values of C-reactive protein, lactate, albumin, alkaline phosphate, neutrophils, and regular monitoring of blood glucose levels may play a critical role in the outcome of the disease." (PMID 36059615, 2022). "Additionally, plasma CRP, IL-6, and lipoprotein-associated phospholipase A2 levels were significantly higher in diabetes patients with MCI compared to T2DM controls without MCI." (PMID 35682821, 2022). "Subgroup analyses of individuals with Stage 3a-5 kidney disease that were: first wave patients; aged 65–74 and 85–94; female sex; never and current smoker; CRP ≥ 40 mg/dL; no hypertension; no diabetes; CFS 4 and CFS 5–6 were associated with increased mortality." (PMID 35151257, 2022). "Partial correlation corrected for age, BMI, liver steatosis, diabetes and LDL revealed significant associations of serum PCSK9 with the MELD score (r = −0.395, p = 0.031), bilirubin (r = −0.372, p = 0.043), leukocyte count (r = 0.521, p = 0.003) and CRP (r = −0.459, p = 0.011)." (PMID 33920491, 2021). "Our study hypothesis is that the saliva inflammatory biomarkers will be higher in Type 2 diabetics and our study investigated the association between salivary levels of selected salivary inflammatory biomarkers (CRP, IL-6 and TNFα) in type 2 diabetes mellitus and glycaemic control." (PMID 33676486, 2021). "To investigate whether the CT score had an independent correlation with the worse outcome, we adjusted this relationship for the confounding factors namely diabetes mellitus, hypertension, pre-renal azotemia, BMI, and hs-CRP using the multiple logistic regression analysis." (PMID 33788067, 2021). "Whether serum PCT correlates with cardiovascular risk and how it compares to other markers such as serum CRP especially in patients with diabetes has not previously been demonstrated." (PMID 34725609, 2021). "However, very few studies have been done on the relation between high sensitivity CRP and diabetes." (PMID 34868746, 2021). "Although inflammation assessed by elevated C reactive protein (CRP) concentration is known to be associated with risk of cardiovascular disease, its association with microvascular and macrovascular dysfunction in diabetes and non-diabetes remains unclear." (PMID 32665312, 2020). "In conclusion, this study demonstrates that elevated levels of CRP and uric acid are positively associated with the risk of developing diabetes independent of metabolic risk as defined by elevated and or abnormal cholesterol, blood pressure, and waist circumference." (PMID 32879892, 2020). "Furthermore, persons with diabetes had a significantly higher C-reactive protein value (p = 0.034)." (PMID 31924175, 2020). "However, they did not evaluate the association between changes in CRP and the risk of incident diabetes." (PMID 32612667, 2020).
diabetes (continued). "Clinical studies found that proinflammatory factors such as interleukin-6 (IL-6) and C-reactive protein (CRP) were significantly higher for the population who developed diagnosed diabetes over the follow-up period, and to some degree, these indicators could be used as powerful predictors of T2D." (PMID 33224253, 2020). "Another study from Puerto Rico showed an inverse association between BP-3 and c-reactive protein, a marker for systematic inflammation commonly perceived as a predictor for diabetes; but again, their outcome was not glucose levels or diabetes, and the study was cross-sectional." (PMID 32345324, 2020). "Furthermore, in the logistic model, serum HSP27 levels were found to be independent predictors for carotid IMT in type 2 diabetic patients after adjustment for onset age of diabetes, blood pressure, total cholesterol and C-reactive protein (OR = 1.085, P = 0.022)." (PMID 32334520, 2020). "Cell surface GRP78 can be shed and circulating GRP78 levels were found to be increased in subjects with diabetes and obesity and to correlate with CRP levels, suggesting that the chronic inflammation could be a contributing factor to the observed increase in addition to the metabolic stress." (PMID 33042029, 2020). "Previous studies have reported that the elevated levels of hs-CRP could increase the risk of CKD among people with or without diabetes, while the evidence was not consistent." (PMID 32587865, 2020). "The present prediction model, which requires only seven variables and includes Sex, diabetes history, anastomotic type, reconstruction route, smoking history, CRP level and presence of cardiac arrhythmia, may be useful for predicting anastomotic leakage in patients after oesophagectomy." (PMID 32252738, 2020). "Clinically, patients with diabetes mellitus have a systemic inflammatory process in the development of polyneuropathy, evidence of which was provided by sensitive specific markers (increased synthesis of proinflammatory cytokines, C-reactive protein, proliferation of macrophages)." (PMID 32831065, 2020). "Considering the persistence of a statistically significant association between higher CRP concentration and higher odds of diabetes after excluding individuals with CRP concentrations >10 mg/L, our results could reflect the role of subclinical inflammation, instead of acute infection." (PMID 32665312, 2020). "In individuals with obesity or diabetes, circulating levels of GDF-15 are higher than in unaffected individuals, and are positively correlated with blood concentrations of glucose, HbA1c, insulin resistance, C-reactive protein (CRP) and other cardiovascular risk factors." (PMID 30350239, 2019). "In healthy population and in those with different chronic diseases like diabetes, atherosclerosis and polyarthritis, the higher concentrations of 25(OH)D have been correlated with lower status of inflammatory biomarkers including interleukin 6, CRP, and tumor necrosis factor alpha." (PMID 30791895, 2019). "In univariate analyses, SBI (+) group was associated with age, hypertension, diabetes, antiplatelet medication, ICAS, and levels of fasting glucose, TC, LDL cholesterol, HDL cholesterol, TG, non-HDL cholesterol, TG/HDL cholesterol ratio, TC/TG ratio, and hs-CRP." (PMID 31266453, 2019). "In addition, the participants in two articles had carotid atherosclerosis/intima thickening and dyslipidaemia; in four other studies, the participants exhibited aortic stenosis, a high level of hs-CRP, a high level of hs-CRP/dyslipidaemia, and cerebrovascular diseases/diabetes." (PMID 30834266, 2019). "Forty-nine (41.5%) patients belonged to the high AS group and had a higher incidence of diabetes mellitus (DM) and increased systolic blood pressure, serum C-reactive protein, and PC levels but had lower creatinine, compared with those in the control group." (PMID 31877718, 2019).